IL10 (interleukin 10)
Diseases named in the same sentence as IL10 in open-access papers (continued):
Sharing a sentence is not in itself a finding about the gene and the disease.
tumor (continued). "We have to note the significantly higher amount of cells expressing IL10 in the tumor stroma of patients exposed to wide spectrum beta-blockers." (PMID 32353988, 2020). "IFN-γ is a pro-inflammatory cytokine produced predominantly by T and NK cells, whereas IL10 is an anti-inflammatory one that can also be produced by tumor cells including melanoma." (PMID 33077770, 2020). "Conversely, mediators released by MC such as FGF-2, NGF, PDGF, VEGF, IL-8, and IL-10 promote the expansion of tumor cells." (PMID 31256327, 2020). "M2-like TAMs contribute to tumor progression by expressing VEGFα to benefit angiogenic process, producing MMP9 to promote tumor invasion, secreting IL-10 and TGFβ to maintain an immunosuppressive microenvironment." (PMID 33260160, 2020). "We included both anti- and pro-inflammatory cytokines involved in tumor suppression such as TNF-α, IL-1β, and tumor promotion such as IL-10, CCL22, CXCL5, and TGF-β (selection of cytokines based on ref.)." (PMID 33267818, 2020). "Bregs exert a suppressive potential towards many cells, including T cells, via secreting anti-inflammatory mediators, such as IL-10, and also potentiate the conversion of T cells into Tregs with subsequent attenuation of the anti-tumor immune responses." (PMID 32664587, 2020). "Various cytokines (e.g., IL-6, IL-10, and IL-11) that are released into the microenvironment by tumor cells have also been shown to activate STAT3." (PMID 32188095, 2020). "In murine xenograft tumor models, lipoxin A4 is able to suppress tumor growth by targeting immune-suppressive IL-10-producing regulatory B cells via dephosphorylation of STAT-3 and extracellular signal-regulated kinase." (PMID 32676076, 2020). "IL-10 is usually regarded as an anti-inflammatory cytokine and has been reported to exert anti-tumor effects through the increasing tumor antigen-specific CD8+ T cell infiltration and the INF-γ-mediated induction of antigen presentation." (PMID 33322487, 2020). "M2 activation, which is considered to be a tumor-promoting state, is characterized by the production of arginase, IL-10, and specific membrane proteins like MRC1 and CD163." (PMID 32708944, 2020). "Apparently, ibrutinib targets Bruton’s tyrosine kinase from the surface of TAMs from the CLL microenvironment, modifying their function and stimulating them to produce IL-10, providing the tumor cells with resistance to treatment." (PMID 33228048, 2020). "In these co-cultures of tumour cells and monocytes, we detected upregulation of cytokines (TNFα, MCP-1, IL-10, CXCL-10, IL-1β, IL-6, IL-23) associated with MOv18 IgE ADCC compared to isotype control-triggered cytotoxicity." (PMID 33203088, 2020). "Despite being historically associated with immune suppression, different studies showed a protective effect of IL10 against tumor progression." (PMID 32353988, 2020). "M1 TAMs, characterized by high expression of IL-12 and low expression of IL-10, can present tumour-specific antigen and inhibit tumour development." (PMID 33287740, 2020). "The contact of mature DCs with tumor-derived factors can induce Treg1-like cells from naive CD4+ T cells through high IL-10 and low IL-12 signaling." (PMID 33036244, 2020). "It is well known that IL-10 produced by macrophages decreases the anti-tumor T cell response and facilitates tumor growth." (PMID 32222879, 2020). "Accordingly, genetic inactivation of the signal transducer and activator of transcription 3 (Stat3) in macrophages, leading to the inactivation of anti-inflammatory IL-10 signaling, has resulted in chronic intestinal inflammation and onset of tumor lesions." (PMID 32962159, 2020). "Because IL10 polarizes tumor-associated macrophages (TAMs) into the immunosuppressive, M2 phenotype, multiple EBV-related proteins end up blunting the anti-tumor potential of inflammatory cells." (PMID 33327433, 2020).
tumor (continued). "Conversely, low-dose CTX enhances the immune response against various tumor antigens by suppressing regulatory T cells (Treg cells) and down-regulating interleukin (IL)-10." (PMID 32104586, 2020). "The expression of IL-10 inhibits the activation of T cells and natural killer (NK) cells, resulting in the proliferation and activation of tumor cells." (PMID 32731404, 2020). "The overall effect of IL-10 secreted by TAM on GBM is immunosuppression which ultimately promotes a pro-tumor milieu." (PMID 32765498, 2020). "This polarization was verified by decreased level of IL-10 (M2 marker) and increased level of IL-12 (M1 marker) within the tumor." (PMID 32999291, 2020). "Removing IL-10 in co-cultures of monocytes and tumor cells can reduce the upregulation of PD-L1 in monocytes and affect the curative effect of the immune checkpoint inhibitors." (PMID 32655621, 2020). "PXA3-FKHR interacted with STAT3 to reduce the expression of MHC and generate immunoinhibitory secreted factors such as IL-10 in tumor cells." (PMID 32872659, 2020). "In this study, the variance of factorial design revealed that the expression of TGF-β1 and IL-10 in the supernatant of mouse tumor tissues decreased after treatment with endostar and radiotherapy, with statistically significant differences (p < 0.05)." (PMID 32669133, 2020). "IL10 has potent anti-angiogenic activity and can inhibit the growth and metastasis of tumor cell by promoting apoptosis and inducing tumor cell differentiation." (PMID 32742480, 2020). "Our results demonstrated that the level of NMU mRNA in HCC peri- and intra-tumor tissue was positively related to the levels of type-2 cytokine mRNA, including IL-4, IL-10, and IL-13." (PMID 32013887, 2020). "Preclinical cancer models show that TIGIT is highly upregulated in tumor infiltrating lymphocytes, where it marks a exhausted/dysfunctional T cell population able to produce IL-10." (PMID 33027962, 2020). "In contrast to IL-1β and IL-4, IL-10 overexpression elicits tumor rejection by stimulating cytotoxicity of CD8 (+) T cells by inducing the expression of IFN-γ in CD8 (+) T cells." (PMID 33112542, 2020). "In EOC tumors and ascites, TAM are characterized by the expression of M2-related markers, such as CD163, CD204, CD206 and IL-10, and their presence correlates with tumor progression and poor patient survival." (PMID 32630708, 2020). "The results showed tumor angiogenesis were inhibited in mice with MSCs-IL10 compared to the mice injected with empty-vector, as well as only MSC (P < 0.001), and the FITC-labeled dextran intake was also lower than that in the other groups (P < 0.01)." (PMID 32742480, 2020). "It has also been shown that MDSCs can inhibit anti-tumour immune responses by driving the expansion of Treg cells in a cell-to-cell contact independent manner, at least in part, by inducing the secretion of IL-10 upon activation of STAT3 pathway." (PMID 32931721, 2020). "Alternatively, activated macrophages (M2) are stimulated by IL-4 and IL-13 and are involved in tissue repair, suppression of inflammation and tumor progression by secreting the anti-inflammatory cytokines IL-10 and TGF-β." (PMID 32184778, 2020). "The immunosuppressive cytokine, IL-10, released by the regulatory T-cells and tumor cells, can lead to a defective antigen presentation capacity of dendritic cells (or macrophages), corresponding to reduced T-cell activation." (PMID 33256089, 2020). "For example, STAT3 increased CTLA-4 expression in tumor-associated B cells in a JAK-dependent manner and enhanced CTLA-4 expression in Treg cells through IL-10." (PMID 32972405, 2020). "To investigate the effect of HO-1 on tumor-related inflammation, we measured the concentration of IL-6, IL-10, IL-12, MCP-1 and IFNγ in serum using the BDTM CBA Mouse Inflammation kit." (PMID 33287312, 2020).
tumor (continued). "For instance, in tumor immunity, IL-10 signaling pathways plays a dual role that IL-10 promotes tumor immune escape by inhibiting inflammatory cytokines, and conversely induces tumor-specific CD8+ T cells infiltration and promotes their cytotoxic activity." (PMID 32021566, 2020). "This underscores the role of LAP plays in IL-10 expression and provides a potential target to regulating the pro-tumor cytokine in tumor cells." (PMID 32850405, 2020). "IL-10 protects the tumor, while inhibiting the chemotaxis of neutrophils, monocytes and dendritic cells in the TME, by suppressing the CC and CXC chemokines." (PMID 33228048, 2020). "Th2 cytokines such as IL-4, IL-10, IL-13, and Tgf-β that inhibit anti-tumor responses can also be released by myeloid derived suppressor cells (MDSC) that have been activated by tumor cells." (PMID 32508830, 2020). "In response to tumor-derived inflammatory stimulation, T reg cells secrete anti-inflammatory interleukin-10 (IL-10) and transforming growth factor β (TGF-β) in order to dampen an inflammatory immune response against the tumor." (PMID 33329549, 2020). "IL-10, a further anti-inflammatory cytokine, is produced by both M2 macrophages and by the tumor cells." (PMID 32850405, 2020). "Although a large amount of evidence points towards radiotherapy stimulating an anti-tumor immune response, radiotherapy can also unfortunately result in the secretion of immunosuppressive cytokines such as IL-6 and IL-10 from treated tumor cells." (PMID 33178210, 2020). "Conversely, M2-type macrophages are activated by IL4 and IL10 and exert anti-inflammatory and sometimes tumor-promoting effects." (PMID 32707869, 2020). "These polarized cells create a feedback cycle through MDSCs modification and enhance IL-10 production, which will subsequently facilitate the tumor growth." (PMID 33133086, 2020). "M2 macrophages release anti-inflammatory cytokines, such as IL-10, promoting tumor cells proliferation and protecting malignant cells from chemotherapy induced apoptosis." (PMID 32548715, 2020). "IL-10-treated DCs can then suppress anti-tumour adaptive immunity by inhibiting T cell responses upon ligation of PD-1 on T cells with its ligand ‘PD-L1' on DCs." (PMID 32931721, 2020). "IL-10 produced by DCs exert autocrine effects to suppress cross-priming of tumor-specific CD8+ T cells." (PMID 32132993, 2020). "In short GCTSCs contribution for tumor proliferation via promoting macrophages M2 phenotype polarization by improving IL-6 and IL-10 secretion." (PMID 32904108, 2020). "CD163 is a macrophage- and bone marrow-derived monocyte-specific transmembrane protein whose expression is induced by tumor promoting cytokines, such as IL-6 and IL-10, and reduced by inflammatory stimuli, including TNF-α and IFN-γ." (PMID 33212945, 2020). "Some findings indicate that in the tumor microenvironment PD-L1 is correlated with the expression level of IL-10." (PMID 32727138, 2020). "These NPs led to a decrease in macrophage number in tumors, reduced tumor size, IL-10, and TGF-β, while an increase in CD8+ T cells." (PMID 33050070, 2020). "Tumor cell-derived HMGB1 suppresses naturally acquired CD8+ T cell-dependent antitumor immunity by stimulating Tregs to produce IL-10, which is necessary for Treg-mediated immunosuppression." (PMID 32551121, 2020). "Down-regulation of gene expression of M2 polarization markers, ARG1, IL-10, and IL-4, was observed in tumor." (PMID 33194645, 2020). "In terms of cytokines, here we demonstrated that Wnt5a stimulated macrophages to produce IL-10, which in turn induced M2 polarization of macrophages, finally facilitating tumor growth, invasion and metastasis." (PMID 32228612, 2020). "GBM tumor cells also secrete the anti-inflammatory cytokine IL-10 which, in the normal setting prevents excessive inflammation and reduces tissue damage by suppressing the activity of Th1 and CD8+ T cells." (PMID 33178210, 2020).
tumor (continued). "Tumoral invasion is possible through the contribution of IL-10 by inhibiting the function of macrophages and dendritic cells that are responsible for presenting the tumor antigen to T lymphocytes." (PMID 32899735, 2020). "This was, at least in part, through production of high levels of IL-10, at different anatomical sites including peripheral blood, lymph nodes and tumour tissues with a positive correlation between MDSC/IL-10 levels and disease progression." (PMID 32931721, 2020). "In contrast, M2 macrophages are activated by IL-4, IL-13, IL-10, and glucocorticoid hormones, produce high levels of IL-10 and low levels of IL-12, and promote tumor progression." (PMID 32471499, 2020). "It is postulated that IL-10 in the tumor microenvironment contributes to the silencing of immune response and polarization of macrophages to M2 class, with a suppressor and pro-tumoral properties." (PMID 32887237, 2020). "In particular, in the secretome of BDCs of subjects with advanced tumours, IL-10, VEGF, and IL-1 beta are prevalently present." (PMID 32630302, 2020). "M2 TAMs express CD163, CD115, and CD206; they are able to secrete IL-10, promote tumor growth, and foster angiogenesis." (PMID 32532153, 2020). "The survival benefits of STAT3 inhibition have been shown in a GL261 model, where the expression of cytokines promoting tumour growth, such as IL‐10 and IL‐6, was blocked." (PMID 32567735, 2020). "M2 macrophages also contribute to the immunosuppresive microenvironment of the tumor through the expression of immunosuppressive signaling molecules, such as IL-10 and TGF-ß33." (PMID 33067480, 2020). "A reduced number of CD11b+ and CD115+ cells resulted in an increased number of T cells infiltrating the tumor, a lower number of IL-10-releasing CD4+ T cells and a smaller Treg population." (PMID 32488850, 2020). "In contrast, M2 macrophages express high levels of IL-10 and low levels of IL-12, are activated by IL-4, IL-10, IL-13 and glucocorticoid hormones and promote tumor progression." (PMID 32878277, 2020). "Mechanistically, Wnt5a induced M2 polarization of TAMs by regulating CaMKII-ERK1/2-STAT3 pathway-mediated IL-10 secretion, thereby promoting tumor growth, invasion and metastasis of CRC." (PMID 32228612, 2020). "Notch1 expression was also increased and Ikaros/IRF8 expression decreased in the DN2 population isolated from tumor-bearing IL-10−/− mice as compared to wild-type tumor-bearing mice." (PMID 32582141, 2020). "In part, HMGB1 enhances the suppressive activity of MDSCs by enhancing their capacity to produce IL-10 which, in turn, suppresses anti-tumour immunity and polarizes the activation of pro-tumour immune phenotype." (PMID 32931721, 2020). "Clinical analysis shows poor prognosis of melanoma patients with high levels of IL-10 in the serum and tumor tissue." (PMID 32670290, 2020). "Generally, the concentration of macrophage derived IL-10 is almost 10 fold higher than that from leukocytes within the tumor, playing a role in immune suppression in tumors, which is related to tumor drug resistance, cellular growth and proliferation." (PMID 32727138, 2020). "Cytokines such as Interleukin 6 (IL-6), Tumor Necrosis Factor alpha (TNF-α), Interleukin- 1β (IL-1β) and Interleukin 10 (IL-10), which are released peripherally and in the tumor microenvironment, can act locally in reciprocal signaling interactions." (PMID 33126617, 2020). "Here we studied the relevance of inflammation, intestinal tumor localization and bacterial proximity in a novel mouse model, crossing MSH2loxP/loxP Vil‐cre mice with IL‐10−/− mice." (PMID 32350866, 2020). "Genetic ablation of other complement proteins such as C3 was also shown to have profound inhibitory effects on primary tumor growth and metastasis correlating to increased numbers of IFNγ+/TNFα+/IL10+ CD4+ and CD8+ T-cells." (PMID 33718121, 2020).
tumor (continued). "Earlier study found elevated expression of HLA-G and IL-10 in tumour sites and low levels of soluble HLA-G in saliva samples in OSCC17." (PMID 32123232, 2020). "In PC TME hypoxic conditions and aPSC-derived cytokines, such as IL-10 and IL-13, polarize macrophages towards a M2, pro-tumor phenotype." (PMID 32012917, 2020). "The level of tumor pro-growth cytokine, IL-10 was reduced to 291 ± 1.5 pg/mL in NLC-Citral from 360 ± 0.8 pg/mL in NLC-Blank and 331 ± 0.40 pg/mL in citral-treated mice." (PMID 32526880, 2020). "The TME consists of cancer cells as well as immunosuppressive cells and their associated cytokines, i.e., interleukin-10 (IL-10) and transforming growth factor-β (TGF-β) that facilitate tumor progression and mediate T cell dysfunction." (PMID 32117960, 2020). "IL10R, expressed on CD8 T cells, is necessary for the IL10-mediated tumor regression and the in-situ proliferation of CD8 T cells." (PMID 33381115, 2020). "MDSCs isolated from tumor with a heightened IL-1β level produce more IL-10 and downregulate IL-12 by macrophages to a greater degree as compared with MDSCs from less inflammatory tumors." (PMID 32793192, 2020). "These newly recruited DCs secreted more IL-12 and less IL-10 compared with those from untreated animals and were able to induce anti-tumor T-cell responses in a colon cancer model." (PMID 32656079, 2020). "Tumor and tumor-infiltrating cells are known to secrete various molecules, such as angiogenic IL-8, immunomodulatory IL-10, and TGF-β, all of which have both angiogenic and immunomodulatory functions." (PMID 32823915, 2020). "IL-10 can promote tumor growth and the clinical utility of inhibiting this effect is widely reported." (PMID 32850405, 2020). "They stated that BMP-6 (bone morphogenetic proteins-6) stimulated TAMs to produce IL-10, which then induced M2 polarization of TAMs to mediate the pro-tumor effect of BMP-6." (PMID 32228612, 2020). "Given the distinct contributions of each cytokine to tumor escape and graft prolongation, these findings raised a key question: Why is the Treg cell unable to make both IL-35 and IL-10 at the same time?" (PMID 32983104, 2020). "Our results suggest that tumor-induced arrest of DN2 T cells in the thymus is correlated with a significant increase in il-10 transcription and a coordinated reduction in il-7 and il-15 transcription." (PMID 32582141, 2020). "Of note, we found increased levels of several immunosuppressive cytokines such as Tslp, transforming growth factor β (Tgfβ), Il10, and Inos as well as of pro‐inflammatory cytokines such as Tnfα, Il1β, Ifnγ, and Il17 in tumor lesions compared to control skin." (PMID 32615027, 2020). "This knowledge led us to evaluate the concentration of Th-1 (IFN-γ, IL-2) and Th-2 (IL-10, IL-4) serum cytokines in M-406 bearing CBi/L mice, in the different stages of tumor immunoediting." (PMID 33312693, 2020). "Mast cells produce Th2 cytokines which contributes to M2 (pro-tumor) polarization of tumor-associated macrophages, and the cells produce TNF-α and IL-10 which promote the Treg-mediated immune tolerance and immune tolerance against tumors." (PMID 32023940, 2020). "Although IL-10 has immunosuppressive effects on NK cells, it has pleotropic effects on the regulation of tumor-promoting inflammation, and thus has been tested in clinical trials to augment CD8+ T-cell function against cancer." (PMID 32153582, 2020). "On the contrary, M2 TAMs, with high expression of IL-10 and low expression of IL-12, is a vital subtype which can promote tumor growth and chemoresistance." (PMID 33287740, 2020). "The gene expression levels of VEGF, TGF-β, PGE2, and IL-10 in tumor cells from untreated, lent-miR-138-5p treated, and lent-NC treated A549 bearing mice were determined by RT-QPCR." (PMID 32754587, 2020).